PFKFB3 (6-phosphofructo-2-kinase/fructose-2,6-biphosphatase 3)
Diseases named in the same sentence as PFKFB3 in open-access papers (continued):
Sharing a sentence is not in itself a finding about the gene and the disease.
tumor (continued). "Treatment with PFKFB3 inhibitor 3PO showed a reduction in tumor size in HER2+ mouse model of BC." (PMID 32806533, 2020). "This proves that HER2 modulates tumor glycolysis by regulating PFKFB3 expression." (PMID 32806533, 2020). "The dual role of autophagy in tumor progression highlights the importance in identifying those tumors most likely to respond to autophagy inhibition as compared to those tumors likely to progress through a Pfkfb3-dependent mechanism." (PMID 31413316, 2019). "Besides, PFKFB3 is also identified in glycolysis, cell proliferation, and tumor growth in the procession of tumor and inflammation." (PMID 31455417, 2019). "Moreover, PFK15, a selective PFKFB3 inhibitor, significantly inhibited tumor growth in a xenograft model of human HCC." (PMID 29559632, 2018). "Inhibition of PFKFB3 sensitizes tumor to cisplatin treatment in a xenograft model." (PMID 29410405, 2018). "Our work suggests that nuclear localized PFKFB3 may serve as an important node in sensing nuclear stress and signaling cytoplasmic glycolytic control that may have been exploited by tumor cells." (PMID 29410405, 2018). "PFKFB3 has been reported to play important roles in promoting tumor cell growth." (PMID 29410405, 2018). "PFKFB3 inhibition inhibited tumor growth, suggesting that PFKFB3 may be a potential target for HCC treatment and may play a role in overcoming resistance to chemotherapy." (PMID 29559632, 2018). "Furthermore, inhibition of PFKFB3 impairs pathological angiogenesis and induces tumor vessel normalization, leading to reduced metastasis and improved chemotherapy." (PMID 29410405, 2018). "PFKFB3 gene expresses an isoenzyme that has high kinase and low bisphosphatase activity (K/B = 710), favoring the net synthesis of Fru-2,6-P2 and eliciting high concentrations of this metabolite in proliferating and tumor cells." (PMID 30234009, 2018). "PFKFB3 inhibitors also promote cell quiescence and tighter cell–cell junctions, resulting in a tighter pericyte layer covering the endothelial cell layer and leading to the maturation and normalization of the tumor vasculature." (PMID 29719532, 2018). "It was noted that PFKFB3 mainly located in the nucleus of tumor cells in human HCC specimens." (PMID 29559632, 2018). "Although it has previously been shown that VEGF secreted from hypoxic glioma tumor cells can increase GLUT1 expression in ECs, several other factors that are present in the tumor microenvironment such as cytokines, hypoxia and estrogen can also increase EC PFKFB3 expression." (PMID 30255018, 2018). "Aerobic glycolysis undergoes cytoplasm, so we hypothesized that PFKFB3 mainly regulated HCC growth in the nucleus of tumor cells." (PMID 29559632, 2018). "Two mechanisms may involve the suppression of tumor cell proliferation by inhibition of PFKFB3 expression." (PMID 29559632, 2018). "Our results indicated that GZZSZTW significantly increased the expression levels of multiple genes involved in promoting cell proliferation, most of which are highly expressed in tumor cells, such as Tnfaip2, Chi3l1, Tnf, Pfkfb3, Sox8, Jag1, Mafb, Pla2g7, Hnrnpa1, and E2f3." (PMID 30275866, 2018). "Moreover, the selective antagonist of PFKFB3 slows down the growth of transplanted tumor in several animal models." (PMID 28061878, 2017). "We also tested the therapeutic efficacy of PFK15 by establishing HNSCC xenograft and metastasis nude mice models, and found that targeting PFKFB3 offered a promising therapeutic strategy not only for suppressing primary tumor growth but also for alleviating distant metastasis in HNSCC." (PMID 28061878, 2017). "Apart from mediating glycolysis acceleration, PFKFB3 might also involve in other tumor progressions." (PMID 28061878, 2017).
tumor (continued). "The fluorescent images clearly showed that although most of PFKFB3 was localised in the nuclei of the tumor cells, the positive staining of PFKFB3 could also be detected in the invadopodia." (PMID 28061878, 2017). "Not only that, the transcription of PFKFB3 in CSCs were even higher than in tumor cells." (PMID 28977989, 2017). "Therefore, increasing numbers of researchers focused on the role of PFKFB3 in the regulation of tumor cell proliferation and metabolism." (PMID 28977989, 2017). "Even though the role of PFKFB3 in regulating the process of autophagy is unexpected and controversial, the combination of PFKFB3 inhibitors with autophagy inhibitors has been proven to be effective on certain tumor cells." (PMID 28977989, 2017). "In sum, using PFK15 to inhibit glycolysis in HNSCC cells could also dramatically suppress cell migration and invasion, suggesting that blockage of PFKFB3 was a promising prospect against tumor metastasis in HNSCC." (PMID 28061878, 2017). "miR-26b and miR-206 inhibit tumor growth via the downregulation of PFKFB3-driven glycolysis." (PMID 26918353, 2016). "PFKFB3 is overexpressed in some tumors, and its silencing prevents cells from entering the S phase and decreases glucose uptake as well as inducing autophagy in order to decrease tumor burden." (PMID 26337471, 2015). "Here, we hypothesize that CSCs can be distinguished from iPS or from other cancer cells within the bulk of the tumor on the basis of PFKFB3 and PFK1 expression, and we show the differences between CSCs and iPS in PFKFB3 and PFK1 expression." (PMID 26337471, 2015). "In this work, we show that autophagy is induced by PFKFB3 inhibition and that this induction is likely serving as a resistance mechanism given the observed increase in apoptosis in vitro and decrease in tumor growth in vivo mediated by pharmacologic inhibitors of autophagy." (PMID 24451478, 2014). "We hypothesized that the functional glucose starvation induced by inhibition of PFKFB3 in tumor cells would induce autophagy as a pro-survival mechanism and that inhibitors of autophagy could increase the anti-tumor effects of PFKFB3 inhibitors." (PMID 24451478, 2014). "In addition, we examined uptake of [18F]-FDG in PFKFB4 shRNA and control tumors by PET scan and observed reduced tumor [18F]-FDG uptake in the PFKFB4 shRNA tumors as has also been described as a result of PFKFB3 inhibition." (PMID 25115398, 2014). "Along this line, PFKFB3 targeting was recently extended to tumor implantation models." (PMID 25250177, 2014). "Indeed, pharmacological blockade with 3-(3-pyridinyl)-1-(4-pyridinyl)-2-propen-1-one (3PO) or EC-specific genetic silencing of PFKFB3 inhibits tumor growth in vivo." (PMID 25063693, 2014). "A noticeable finding was that expression of certain genes involved in tumor cell metabolism including 6-phosphofructo-2-kinase/fructose-2,6-biphosphatase 3 and 4 (PFKFB3 and PFKFB4), and pyruvate dehydrogenase kinase isoenzyme 1 (PDK1) was rapidly diminished when MTG16 was expressed." (PMID 23840896, 2013). "Small molecule inhibitors of PFKFB3 have been identified and shown to inhibit tumor cell growth." (PMID 23776707, 2013). "Accordingly, it has been hypothesized that inhibition of PFKFB3 would deprive tumor cells of energy sources necessary for proliferation and growth." (PMID 21957443, 2011). "The other six genes with more than two-fold upregulation in more than five tumours arrayed were CCNG2 in 30 tumours, NDRG1 in 18 tumours, PFKFB3 in 17 tumours, RNAse4 in 10 tumours, Adrenomedullin (ADM) in eight tumours and Glucose transporter 1 (GLUT-1) in six tumours." (PMID 16052224, 2005). "We were unable to find the same association between PFKFB3 and prognosis, and this could be due to the lack of more aggressive tumor stages in our dataset." (PMID 40022029, 2025). "Therefore, TZP might interfere with this pathway to reduce glucose uptake in tumor cells and downregulate PFKFB3 and PFK1, thereby limiting their growth." (PMID 40125821, 2025).
tumor (continued). "However, by delivering fructose −1,6- diphosphate (F16bp, downstream product of PFKFB3), the glycolytic ability and function of DCs can be “saved”, the anti-tumor response of activating cytotoxic T cells (Tc) can be enhanced, and the survival of mice can be improved." (PMID 41000074, 2025). "Knowledge of the vital role of PFKFB3 in regulating glycolysis, accumulating evidence has demonstrated that PFKFB3 participated in multiple cancer events, including carcinogenesis, cancer cell proliferation, vessel aggressiveness, drug resistance, and tumor microenvironment." (PMID 38622715, 2024). "Based on the presence and high expression of PFKFB4 in these lung tumors and the longer period of decreased PFKFB3 expression, we speculate that PFKFB4 may compensate for the loss of PFKFB3 to support cell cycle progression, proliferation, and tumor growth in this model." (PMID 39001392, 2024). "Hence, the use of 3PO as a PFKFB3 inhibitor could assist (C)RT by reversing the metabolic state of tumor and endothelial cells, thereby promoting tumor vessel normalization (TVN) to improve oxygenation and radiotherapy efficacy." (PMID 39007350, 2024). "Furthermore, targeting LINC00930 and PFKFB3 during radiotherapy accelerates tumor shrinkage." (PMID 38789960, 2024). "Importantly, these data indicate that simultaneous Pfkfb3 and Pfkfb4 deletion and/or inhibition may significantly inhibit tumor growth, which is a focus of ongoing studies." (PMID 39001392, 2024). "In addition, inhibiting the glycolytic activator fructose-2,6-diphosphatase 3 (PFKFB3) in ECs not only induces normalization of tumor blood vessels, but also increases the coverage of PCs and the adhesion of tumor blood vessels to ECs, thereby increasing the delivery of chemotherapy drugs." (PMID 37666813, 2023). "However, the downregulation of the expression of PFKFB3 may explain the biological effect of the downregulation of tumor invasion and proliferation by sorafenib despite the upregulation of IL-6 at this time." (PMID 37476196, 2023). "However, the accumulation of 18F-FDG mainly revels the activity of glucose transporters (GLUT) in tumor cells and tissues, the biomarker for tumor glycolysis may play more important role in tumor diagnosis, such as PFKFB3." (PMID 37035116, 2023). "In the later stage of treatment, high dosages of sorafenib could continuously induce the downregulation of IL-6 expression and the upregulation of HIF-1α expression, thereby continuing to downregulate the expression of PFKFB3 and inhibiting tumor growth and invasiveness." (PMID 37476196, 2023). "In addition, PFK1 and PFKFB3 are related to the biosynthesis of tumor cells." (PMID 36994237, 2023). "Thus, lowering PFKFB3-driven glycolysis in TECs normalizes the abnormal tumor vasculature." (PMID 36232355, 2022). "Finally, we wanted to verify whether knockdown of PFKFB3 or ENO2 would abrogate the tumor-promoting effects of PPFIA3." (PMID 34094943, 2021). "In line with this, PFKFB3—a central mediator of glycolysis—has been recognized as an important player within the different aspects of tumorigenesis, not only regulating the survival of tumor cells but also of components within the tumor microenvironment, such as immune and endothelial cells." (PMID 33671096, 2021). "Furthermore, it was recently demonstrated that uncontrolled glycolysis in TECs due to an upregulated expression of glycolysis genes, including the enzyme 6-phosphofructo-2-kinase/fructose-2,6-biphosphatase 3 (PFKFB3), contributes to structural deformities observed in tumor blood vessels." (PMID 31600937, 2019). "Moreover, PFK15, a selective PFKFB3 inhibitor, significantly inhibited tumor growth." (PMID 29559632, 2018).
tumor (continued). "In addition, our finding that etoposide and UV also stimulate K472 acetylation of PFKFB3 suggest a potential broad applicability of PFK15 to enhance the efficacy of additional chemotherapeutic agents for the treatment of different types of tumor." (PMID 29410405, 2018). "Similarly, high doses of the PFKFB3 inhibitor 3PO lead to tumor vessel disintegration." (PMID 30255018, 2018). "In this review, we summarize how key glycolytic regulators, including GLUT1, HK2, PFKFB3, PDK1, and LDHA, are controlled by oncogenic, microenvironmental, and non-coding RNA-mediated pathways to reshape tumor metabolism." (PMID 42317327, 2026). "PFKFB3 is overexpressed in multiple cancers, including breast, colon, and HCC, where it correlates with larger tumor burden and poorer prognosis." (PMID 40818043, 2026). "More recently, second-generation PFKFB3 inhibitors, including PFK158, exhibit pharmacological vigor in both tumor and inflammation models." (PMID 41378888, 2026). "Compared with bevacizumab, ECs are more sensitive to low doses of PFKFB3 and CTAP inhibitors, effectively normalising the tumour vascular system and reducing metastasis." (PMID 40268524, 2025). "Here, we provided evidence that Mettl3 promotes the progression of ovarian, breast and testicle cancers by enhancing the Pfkfb3/lactate/H3K18la/PD-L1 axis, and PLGA-encapsulated Levosimendan synergistically reduces tumor size in combination with CDDP." (PMID 40765834, 2025). "However, the correlation between nuclear PFKFB3 protein and RNA levels was weak (Spearman ρ = 0.37, p < 0.001), which may be due to the immunohistochemical staining assessing nuclear protein in tumor cells and the RNA measurement is whole-cell material from all cells in the tissue punch." (PMID 40022029, 2025). "Immunohistochemistry was performed to detect the expression of HIF‐1α, PFKFB3, and PFK‐1 in the tumor tissues of both groups." (PMID 40125821, 2025). "For instance, metformin, a widely used treatment for diabetic patients, has been shown to inhibit the HIF-1α/PFKFB3/PFK1 pathway in HCC cells, thereby suppressing glycolysis and exerting anti-tumor effects." (PMID 39980550, 2025). "TZP suppressed glucose uptake, and reduced expression of key glycolytic enzymes PFKFB3 and PFK‐1, thereby limiting glycolytic and tricarboxylic acid (TCA) flux, leading to energy deprivation and anti‐tumor effects." (PMID 40125821, 2025). "A large number of tumor cells are characterized by increased PFKFB3 expression, as it is the case in CRC, making PFKFB3 an attractive target for the therapy of RC." (PMID 39007350, 2024). "Deregulation of GLUT1, PFKFB3, and LDHA is known in many forms of cancers and facilitates the high glucose consumption by tumor cells." (PMID 39684459, 2024). "Common changes in differently expressed genes resulted in a significant downregulation of tumor-promoting genes (BCL3, NR6A1, and PFKFB3)." (PMID 38779358, 2024). "The recent developments in PFKFB3 inhibitors, a protein closely related to FAK, have also provided valuable insights into the potential of targeting key metabolic enzymes involved in tumour progression." (PMID 39125028, 2024). "Zhang J’s research team found that simultaneous inhibition of VEGF and glycolysis activator PFKFB3 can significantly prolong the survival of GBM patients and slow down tumor growth." (PMID 39877360, 2024). "Previous studies have established that knockdown or inhibition of PFKFB3 suppresses both sprouting angiogenesis and HCC tumor growth, downstream of pro-angiogenic factors." (PMID 38200582, 2024). "We previously have determined that the PFKFB4 enzyme is co-expressed with PFKFB3 in lung tumors and multiple other tumor types and additionally have observed an increase in PFKFB4 expression when PFKFB3 was silenced." (PMID 39001392, 2024).